WWOX (WW domain containing oxidoreductase)
Diseases named in the same sentence as WWOX in open-access papers (continued):
Sharing a sentence is not in itself a finding about the gene and the disease.
breast tumors (5 papers, 2004 to 2023). "Moreover, we showed that VOPP1 was overexpressed in breast tumors; this overexpression was predominant in tumors that retained WWOX expression and was associated with reduced metastasis-free survival of patients with WWOX-positive tumors." (PMID 30285739, 2018). "Heterozygous deletions of WWOX gene were observed in more than 50% of breast tumors and reached up to 80% in ovarian carcinomas." (PMID 30285739, 2018). "Consistent with this possibility, by studying our series of 448 breast tumors, we found that the alteration of WWOX function, considered either by underexpression of WWOX or by overexpression of VOPP1, affects 81.69% (364/448) of breast tumors." (PMID 30285739, 2018). "(D) Kaplan-Meier curves showing metastasis-free survival rates of patients with tumors expressing high (red line) vs. low (blue line) levels of WWOX mRNA assessed by RT-PCR in breast tumors samples." (PMID 30285739, 2018). "We next examined the concomitant expression of VOPP1 and WWOX in our series of breast tumors." (PMID 30285739, 2018). "We showed that WWOX inhibits MERIT40-induced HR activity, that MERIT40 is overexpressed in breast tumors, and that this overexpression is a marker of poor prognosis in BC." (PMID 37248434, 2023). "Consistent with previous results in breast tumour cell lines, the combined treatment did not increase the level of WWOX mRNA expression (not shown), suggesting that hypermethylation of the WWOX gene promoter might not be common in HCC." (PMID 15266310, 2004).
metabolic syndrome (5 papers, 2014 to 2022). A cluster of metabolic risk factors for CARDIOVASCULAR DISEASES and TYPE 2 DIABETES MELLITUS. "Other studies have shown that the WWOX locus is also associated with other disorders linked to metabolic syndrome, such as obesity susceptibility, hypertension, and coronary artery calcification." (PMID 36271927, 2022). "Data collect from Genome Wide Association Studies (GWAS) and full knock-out (KO) mice models have implicated that WWOX gene may be associated with metabolic syndrome and related conditions that affecting cardiovascular and neurological systems." (PMID 25537520, 2014). "Genotypic and allelic frequencies of TUBB and WWOX SNPs in normal and dyslipidemia groups [n(%)]." (PMID 33612478, 2021). "In this study, we investigated associations between single nucleotide polymorphisms (SNPs) in the tubulin beta class I (TUBB) and WW domain-containing oxidoreductase (WWOX) genes, gene-gene interactions, and gene-environment interactions and dyslipidemia in the Chinese Maonan ethnic group." (PMID 33612478, 2021). "In addition, WWOX gene alteration is associated with low plasma HDL-C levels and aberrant HDL cholesterol and triglyceride levels, which are crucial for the development of metabolic syndromes and increases in the risk of neuronal injury." (PMID 25537520, 2014).
multiple sclerosis (5 papers, 2021 to 2025). A progressive autoimmune disorder affecting the central nervous system resulting in demyelination. "Moreover, loss of function of WWOX leads to hypo-myelinization, with a potential role in multiple sclerosis pathogenesis." (PMID 38161429, 2023).
cervical cancer (4 papers, 2014 to 2023). A primary or metastatic malignant neoplasm involving the cervix. "Regarding the anchorage-independent growth, our observations can be confirmed by another study that investigated WWOX overexpression and knockdown in cervical cancer." (PMID 36979157, 2023). "WWOX also functions as a tumor suppressor in cervical cancer where it induces apoptosis and inhibits proliferation." (PMID 24886479, 2014). "We can still identify some genes related to cervical cancer progression from the samples of the two patients after treatment, including ATF3, GPX3, IL10, IL6, RAD51AP1, MGMT, WWOX." (PMID 37914994, 2023).
colorectal cancer (4 papers, 2016 to 2022). A primary or metastatic malignant neoplasm that affects the colon or rectum. "In colorectal cancer, we predict WWOX as a putative driver in a region that shows SVs in 25% of the samples." (PMID 36163358, 2022). "The expression of CD133, WWOX and E-cadherin and related pathological characteristics in 210 specimens of colorectal cancer." (PMID 28523049, 2017). "In short, we studied the expression of CD133, WWOX and E-cadherin in colorectal cancer and found the expression of CD133 was negatively correlated with WWOX and E-cadherin, and there was positive correlation between WWOX and E-cadherin." (PMID 28523049, 2017). "In 210 specimens of colorectal cancer, the positive expression rate of CD133, E-cadherin and WWOX was 61.9%, 40.5% and 41.9%, respectively." (PMID 28523049, 2017). "Therefore, the aim of the present study was to: 1) detect the expression of CD133, E-cadherin and WWOX in colorectal cancer; 2) evaluate the correlations between E-cadherin, CD133 and WWOX in colorectal cancer, facilitate physicians in predicting the progression and prognosis of the fatal disease." (PMID 28523049, 2017).
gestational diabetes (4 papers, 2021 to 2023). Carbohydrate intolerance first diagnosed during pregnancy. "As a result of our observation in pregnancy-associated diabetes, we proposed that the WWOX gene can be an essential contributor to the pathogenesis of gestational diabetes mellitus (GDM)." (PMID 36271927, 2022). "The obtained results clearly show that decreased expression of WWOX is highly likely to be associated with a predisposition to the development of metabolic disorders such as gestational diabetes and type II diabetes." (PMID 35328751, 2022). "Our previous study suggests a significant contribution of the WWOX gene to glucose metabolism in patients with gestational diabetes mellitus." (PMID 35328751, 2022). "The obtained results suggest a significant contribution of the WWOX gene to glucose metabolism in patients with gestational diabetes." (PMID 33520443, 2021). "However, data on the effects of gestational diabetes on the WWOX/HIF1 α signaling pathway are limited, and the role of the HIF1α pathway in GDM remains unclear." (PMID 38234430, 2023). "Our previous study showed decreased WWOX expression and an increase of HIF1A and its targets glycolysis genes in gestational diabetes mellitus (GDM) patients in comparison to control." (PMID 35328751, 2022). "Although the WW-domain-containing oxidoreductase (WWOX)/Hypoxia-inducible factor 1 (HIF1) pathway is a well-known regulator of cellular glucose and energy metabolism in pathophysiological processes, its role in gestational diabetes mellitus (GDM), remains elusive." (PMID 33520443, 2021).
Hypertension (4 papers, 2012 to 2021). The presence of chronic increased pressure in the systemic arterial system. "Genome based gene analyses have identified WWOX as a hypertension (HTN) susceptibility gene in Asian populations." (PMID 25537520, 2014). "Among them, IGF1, SLC4A4, and WWOX were previously implicated as hypertension candidate genes in humans and mice and are primarily associated with obesity, glucose metabolism, and ion homeostasis, which are well-known mechanisms of blood pressure regulation." (PMID 22479346, 2012). "More recent evidence has suggested important roles of WWOX in the suppression of tumor growth, the regulation of a wide variety of cellular functions, steroid metabolism, and possibly hypertension." (PMID 22479346, 2012). "Four hypertension susceptibility genes, IGF1, SLC4A4, WWOX, and SFMBT1, were found by a statistical permutation procedure, confirmed by gene expression analysis, and further replicated using data from the HKHS." (PMID 22479346, 2012). "One hypertension SNP at time 2, rs11636344, in FBN1 gene and another SNP rs17722281 of WWOX gene from multivariate have been previously found to be associated with hypertension in China population." (PMID 24565370, 2013).
multiple myeloma (4 papers, 2014 to 2022). "In humans, alteration and loss of WWOX has been associated with certain B cell tumors, and most notably Multiple Myeloma (MM)." (PMID 31275852, 2019). "Deletions, translocations, and loss of expression affecting the WWOX gene are a common feature of various B cell neoplasms such as certain B cell lymphomas and multiple myeloma." (PMID 31275852, 2019). "All of these genes, except WWOX which is implicated in apoptosis, are involved in the NF-κB pathway and demonstrate that activation of this signalling pathway is important in myeloma pathogenesis." (PMID 24803933, 2014). "Homozygous WWOX deletions are indicative of poor prognosis and alteration of 16q, which includes deletion of WWOX, were recognized by International Myeloma Working Groups as a recurrent secondary genetic event in high-risk MM." (PMID 31275852, 2019). "The WWOX gene crosses the fragile site fra16d, which is one of the most active common fragile sites, where not only chromosome translocation occurs in multiple myeloma but also homozygous and hemizygous deletion appears in carcinoma and carcinoma-derived cell lines." (PMID 35845924, 2022). "16q deletion is another common event, seen in 35% of myeloma cases, and contains the tumour suppressor genes CYLD and WWOX." (PMID 24803933, 2014).
oral cancer (4 papers, 2016 to 2026). "Five polymorphisms of WWOX gene from 761 male patients with oral cancer and 1199 male cancer-free individuals were genotyped." (PMID 27655721, 2016). "Finally, The SNP rs11545028 (NM_016373.4:c.-5C > T) in the WWOX gene is associated with oral cancer risk." (PMID 37344844, 2023). "Overall, rs11545028 C to T substitution might affect the translational initiation and reduce WWOX mRNA and protein expression and the risk of oral cancer." (PMID 27655721, 2016).
pancreatic adenocarcinoma (4 papers, 2009 to 2016). "Besides, WWOX expression was down-regulated in several types of human cancer tissues cell lines, including pancreatic adenocarcinoma, renal cell carcinoma, endocrine tumors and HCC." (PMID 25708809, 2015).
Parkinson disease (4 papers, 2009 to 2022). A progressive degenerative disorder of the central nervous system characterized by loss of dopamine producing neurons in the substantia nigra and the presence of Lewy bodies in the substantia nigra and locus coeruleus. "Disruptions of glucose transport and metabolism impair neurons’ functionality, which is the case with neurodegenerative diseases, such as Alzheimer’s or Parkinson’s disease, with which WWOX has been associated." (PMID 36271927, 2022). "In addition, ELD-T genes also included some oxidation-reduction genes, such as WW domain containing oxidoreductase, Parkinson disease (autosomal recessive, juvenile) 2, parkin, oxoglutarate (alpha-ketoglutarate) dehydrogenase (lipoamide) and cholesterol 25-hydroxylase." (PMID 26346824, 2015). "In a rat model of Parkinson’s disease, treatment of 1-methyl-4-phenyl-pyridinium (MPP+) rapidly increases complex formation of WWOX and JNK1, followed by nuclear accumulation of WWOX and neuronal death in the cortical and striatal neurons." (PMID 32000863, 2020).
thyroid cancer (4 papers, 2017 to 2026). "To determine the effect of the two missense variants on WWOX protein function, we established two thyroid cancer cell lines (CAL‐62 and BCPAP) with the stable overexpression of wild‐type, P252A, or P282A mutated WWOX protein." (PMID 41124647, 2026). "Finally, low WWOX expression is found to be associated with epithelial‐mesenchymal transition and aggressive phenotype in thyroid cancer." (PMID 41124647, 2026). "Several studies have consistently revealed prominent associations between the polymorphisms of WWOX and the aggressive, poor prognosis of various malignancies, such as urothelial, esophageal squamous cell, hepatocellular, lung, pancreatic, and thyroid cancers 30, 31, 36-41." (PMID 37324196, 2023). "We also detected the expression of the WWOX protein using the collected clinical specimens of thyroid cancer." (PMID 41124647, 2026). "In thyroid cancer, WWOX expression correlated positively with the expression of epithelial marker E‐cadherin, while WWOX expression correlated negatively with the expression of mesenchymal marker fibronectin." (PMID 41124647, 2026). "The results showed that the number of colonies was markedly decreased in both thyroid cancer cells stably overexpressing wild‐type WWOX." (PMID 41124647, 2026). "Similarly, cell viability assay indicated that the over‐expression of wild‐type WWOX inhibited the growth of thyroid cancer cells, but WWOXP252A or WWOXP282A mutants lost the ability to inhibit growth." (PMID 41124647, 2026). "The expression of WWOX was significantly lower in thyroid cancer with late stages." (PMID 41124647, 2026). "In summary, these data indicate that the reduced WWOX protein expression promotes EMT and aggressive phenotype in thyroid cancer." (PMID 41124647, 2026).
autism (3 papers, 2021 to 2024). Persistent deficits in social interaction and communication and interaction as well as a markedly restricted repertoire of activity and interest as well as repetitive patterns of behavior. "GWA studies have also identified WWOX as a risk gene for common neurodegenerative conditions, such as SCZ, AD, and autism." (PMID 38724566, 2024).
bladder urothelial carcinoma (3 papers, 2016 to 2020). "Deletion of WWOX, a tumor suppressor gene, is frequent in esophageal adenocarcinoma (32%) and stomach adenocarcinoma (30.2%) and also observed in other human cancer types such as colon adenocarcinoma, bladder urothelial carcinoma and lung adenocarcinoma." (PMID 32617189, 2020). "The distinct methylation patterns of WWOX could also influence the disease status of lung squamous cell carcinomas, invasive breast carcinomas, normal mammary tissues, and bladder transitional cell carcinomas." (PMID 26910372, 2016). "In addition, we found that the tumor tissues of patients in different varieties of TCGA tumors, such as bladder urothelial carcinoma (BLCA), cholangiocarcinoma (CHOL), and kidney renal clear cell carcinoma (KIRC), also showed lower expression of WWOX compared to normal tissues." (PMID 29905011, 2018).
diabetes (3 papers, 2021 to 2022). "Conceivably, the partnership between WWOX and HIF1α is crucial in the regulation of tumor metabolism and diabetes pathology." (PMID 36271927, 2022). "What is more, as one of the first we focus on the share of the WWOX/HIF1A axis in diabetes." (PMID 35328751, 2022). "This is one of the first reports of the participation of the WWOX/HIF1A axis and the Warburg effect in the pathogenesis of diabetes, therefore further research is definitely needed, which could indicate the potential clinical use of the obtained information." (PMID 35328751, 2022).
disorder of sex differentiation (3 papers, 2019 to 2023). "WWOX pathogenic variants have also been related to sex differentiation disorders (DSD), according to their high expression in reproductive organs and their potential role in gonadotropin synthesis, gonad development, and steroid metabolism." (PMID 38161429, 2023).
Hypoglycemia (3 papers, 2012 to 2024). A decreased concentration of glucose in the blood. "WWOX, which encodes the WW domain-containing protein, is related to hypoglycemia and hyperphosphatemia." (PMID 22479346, 2012).
Intellectual disability (3 papers, 2016 to 2025). "Clinical and molecular characteristics of a consanguineous family show a homozygous mutation of WWOX gene at specific bases, causing a debilitating syndrome characterized by growth retardation, intractable epilepsy, intellectual disability, and early death." (PMID 27495153, 2016).
noninsulin-dependent diabetes mellitus (3 papers, 2021 to 2022). "Therefore, the WWOX/HIF1A lowered expression ratio should be considered as a molecular risk factor for diabetes type 2 and gestational as we already reported." (PMID 35328751, 2022). "In Goto Kakizaki rats, which are a spontaneous model of noninsulin-dependent diabetes mellitus, an increase in activated WWOX levels was detected in the brain cortex of younger rats, while a decrease was observed in older rats." (PMID 36271927, 2022).
Obesity (3 papers, 2012 to 2025). Accumulation of substantial excess body fat. "The single nucleotide variants (SNV) described to be associated with obesity are rs9923451 (16: 1677509940) and rs925642 (4: 187915860) for WWOX and FAT1, respectively." (PMID 35170849, 2022).
Seizure (3 papers, 2021 to 2023). A seizure is an intermittent abnormality of nervous system physiology characterized by a transient occurrence of signs and/or symptoms due to abnormal excessive or synchronous neuronal activity in the brain. "Of utmost concern is that human newborns with WWOX gene deficiency suffer severe neural diseases such as seizure, encephalopathy, and early death." (PMID 35883580, 2022). "Together, these observations suggest WWOX controls cell migration and cell-to-cell recognition and plays a crucial role in neuronal heterotopia that contributes to epileptic seizure." (PMID 35883580, 2022).
squamous cell carcinoma (3 papers, 2013 to 2017). A carcinoma arising from squamous epithelial cells. "A recent study showed that ectopic WWOX is able to suppress autophagy for inducing apoptosis in methotrexate-treated human squamous cell carcinoma, and that induction of WWOX expression in SCC is associated with cure of this cancer in patients." (PMID 27234396, 2013). "The tumor suppressor WWOX (WW domain-containing oxidoreductase) suppresses autophagy in human squamous cell carcinoma." (PMID 28338617, 2017).
acute lymphoblastic leukemia (2 papers, 2013 to 2016). Leukemia with an acute onset, characterized by the presence of lymphoblasts in the bone marrow and the peripheral blood. "In another functional aspect, calcium ionophore/phorbol ester induces terminal maturation of MOLT-4 T cell acute lymphoblastic leukemia, which is due to Ser14 phosphorylation of WWOX, IκBα–ERK–WWOX signaling, and expression of CD3 and CD8." (PMID 27999774, 2016). "The aim of the present study was to analyze the expression of WW-domain oxidoreductase (WWOX), fragile histidine triad (FHIT) and p73 in acute lymphoblastic leukemia (ALL)." (PMID 24137446, 2013).
atherosclerosis (2 papers, 2018 to 2022). A disease characterized by the build-up of fatty material and calcium deposition in the arterial wall resulting in partial or complete occlusion of the arterial lumen. "Thus, this comprehensive examination of WWOX loss in hepatocytes demonstrated overall deregulation of lipid metabolic pathways along with gender specific regulation of HDL and TG metabolism indicating vital implications of WWOX in atherosclerosis and cardiovascular diseases." (PMID 30370248, 2018).
bone cancer (2 papers, 2013 to 2025). A primary or metastatic malignant neoplasm affecting the bone or articular cartilage. "Many outstanding review articles have described the in vitro and in vivo roles of tumor suppressor WW domain-containing oxidoreductase, designated WWOX, FOR, or WOX1, in tumor suppression, metabolic disorders, immune defects, bone tumors, neurodegenerative diseases and others." (PMID 27234396, 2013).
colon adenocarcinoma (2 papers, 2020). "In contrast, in low-grade invasive HT29 colon adenocarcinoma cells, increased WWOX expression promotes cell proliferation but inhibits apoptosis." (PMID 33195192, 2020).
coronary artery calcification (2 papers, 2016 to 2022). Calcification of the coronary artery, used as a measure of coronary atherosclerosis, a risk factor for myocardial infarction. "Genome-wide association study of the gene showed genetic variants in WWOX are correlated with coronary artery calcification." (PMID 36071494, 2022).